TNF (tumor necrosis factor)
Diseases named in the same sentence as TNF in open-access papers (continued):
Sharing a sentence is not in itself a finding about the gene and the disease.
tumor (continued). "We performed co-immunostaining of TNFα and CD68 on 13 GBM samples from patients to detect TNFα expression in GAMs per mm2 of tumor section." (PMID 33853689, 2021). "In a preclinical mouse study, selective deletion of HIF-1α in T cells led to increased tumor growth and decreased T cell tumor infiltration, survival, and effector function, measured by production of TNFα and IFNγ." (PMID 34868044, 2021). "Similar to other tumors, the constitutive activation of NF-κB in PDAC is primarily determined by pro-inflammatory cytokines, such as TNF and IL-1α released by tumor-infiltrating immune cells." (PMID 34572737, 2021). "We also found that PRMT5 deficiency in tumor cells enhanced the secretion of the cytokines IFN-γ and TNF-α by CD4+ T cells, and the expression pattern of above checkpoints on CD4+ T cells was similar to that on CD8+ T cells." (PMID 34522232, 2021). "Salmonella influxes into solid tumors up-regulates the production and release of TNF-α, which leads to tumor hemorrhage and Salmonella invasion, and eventually inhibits tumor angiogenesis." (PMID 33717106, 2021). "Concomitantly, the NK cell secretes other cytokines (IFN-γ, TNF-α) into the surrounding environment; they bind to membrane receptors present on tumor cells to stimulate signaling pathways." (PMID 34452238, 2021). "Conversely, a subset of inflammatory DC which secrete TNF-α and produce nitric oxide are known to be tumor suppressive." (PMID 33986746, 2021). "KEGG pathway analysis showed that DEGs play an important role in the TNF signaling pathway, which was often required for activated monocytes or macrophage cells to kill or inhibit tumor cells." (PMID 33714200, 2021). "A total of 41 TNF-related DEGs including 4 TNFSFs, 18 TNFRSFs, and 19 downstream signal molecules were identified between the tumor and normal groups." (PMID 33643183, 2021). "Other scholars believe that histamine secreted by mast cells can stimulate vascular endothelial cells to produce prostacyclin, which can mediate tumor cell necrosis and inhibit tumor cell metastasis together with TNF-a, IL-1, and IL-6 secreted by mast cells." (PMID 33946045, 2021). "The well-identified tumor-promoting roles of TNFα suggested that this cytokine is an appropriate target for therapy in cancer." (PMID 34201054, 2021). "TNFα, TGF-β, and STAT3 synergistically increased the risk of developing cancers and promoted tumor growth and cancer-associated cachexia." (PMID 34926700, 2021). "Both IFN-γ and TNF-α have been shown to exert effects on not only hematopoietic cells but also tumor vascular ECs and/or stromal fibroblasts, altering tumor vasculature to promote anti-tumor immunity." (PMID 34818534, 2021). "Th1 cells secrete cytokines IFN-γ, TNF-α, IL-12, which play an essential role in tumor immunity, and IL-4, IL-6, and IL-10 are cytokines secreted by Th2 cells, which can inhibit the secretion of cytokines by Th1 cells and promote humoral immunity." (PMID 35071004, 2021). "TNF is now considered a highly pleiotropic cytokine, playing a contextual role in driving either tumour elimination or promotion." (PMID 33446741, 2021). "Elevation of VEGF and TNF-α from normal levels have been observed in various types of cancer, including BC and have been shown to contribute to tumor angiogenesis and metastasization." (PMID 33800754, 2021). "TNFα acts as a pro-tumoral cytokine involved in different processes, such as cell proliferation, tumor progression, migration, epithelial-to-mesenchymal transition (EMT), angiogenesis and metastasis in several cancer types." (PMID 33540543, 2021). "Studies showed that cytokine signaling, including interleukins (IL) such as IL-6, IL-8, and TNF-α, plays an important role in regulating this process by promoting tumor initiation, growth, and cancer progression." (PMID 34573967, 2021).
tumor (continued). "Tumor-associated cells are a potent source of immunomodulating molecules, i.a., pro-inflammatory cytokine IL-1, IL-6, TNF that are involved in the stimulation of key tumor-promoting factors as STAT3 and NF-κB." (PMID 34203461, 2021). "Chemokine-like factor (CKLF)-like MARVEL transmembrane domain-containing 1 (CMTM1) was upregulated in testis and many tumor tissues, and also raised cell proliferation rates and resistance to tumor necrosis factor-α (TNF-α)-induced apoptosis." (PMID 34408975, 2021). "Depending on the milieu, MCs represent a source of either pro-tumorigenic factors favoring angiogenesis and tumor growth or anti-tumorigenic molecules (TNFα and IL-9) with a protective function." (PMID 34282774, 2021). "In a gastric cancer mouse study, tumor cell-derived TNF-α was shown to increase the number of intratumoral mast cells expressing the inhibitory ligand PD-L1 which resulted in the suppression of T-cell immunity." (PMID 34063789, 2021). "Similar results, along with reduced splenic tumor burden and increased splenic pDCs, were obtained by injection of anti-TNFα mAbs in mice with progressive CLL compared to control mice." (PMID 33540543, 2021). "Versican stimulation of TLR2 on macrophages increases the expression of TNF-α, which can sometimes promote tumour progression through mechanisms such as PD-L1 upregulation on both myeloid and tumour cells." (PMID 34527586, 2021). "Meanwhile, several immunostimulatory and inflammatory cytokines were brought into play in tumor suppression, including GM‐CSF, IL‐1β, and TNFα." (PMID 33854892, 2021). "Current research is ongoing to investigate how to target and/or express TNF more selectively within the tumor bed, thus hopefully ameliorating past observed severe systemic side effects." (PMID 34553039, 2021). "NF‐κB is mainly activated in these cells to induce the expression of cytokines (TNFα, IL‐1β, IL‐6, etc.), thereby promoting tumor survival and proliferation." (PMID 34977871, 2021). "Similar to TNFα, IL‐6 is another important and abundant proinflammatory cytokine in the tumor microenvironment." (PMID 34977871, 2021). "Macrophages can contribute to tumor-promoting inflammation, e.g., by secretion of proinflammatory cytokines, like IL-6, IL-1β, TNFα." (PMID 33919517, 2021). "After mice were inoculated with specific PDAC cells and developed tumors, they were treated with PBS Shh, IL-1β, or TNF-α, and the tumor size was measured every week." (PMID 34046348, 2021). "The study pinpointed that MMP-13 expression is upregulated by IL-1alpha and, to a lesser extent, by phorbol myristate acetate, a tumor promoter, and by tumor necrosis factor alpha." (PMID 34204372, 2021). "TNF-α induces tumor cell apoptosis by binding to tumor necrosis factor-related ligands, while binding of Fas ligands on cytotoxic T lymphocytes with their receptors elicits apoptosis." (PMID 34458377, 2021). "Our current and previous studies show that the tumor-promoting aspects of NFκB/TNFα signaling uniformly depend on the induction of PGE2 production and subsequent signaling through EP4." (PMID 33809455, 2021). "In melanoma patients, it was noted that a pH of 6.5 causes a decrease in the expression of TCR component, a decrease in the secretion of IFN, TNF and IL-2, and a decrease in tumor infiltrating T-cell responsiveness." (PMID 33670011, 2021). "Overall, TNF immunocytokines engage anti-tumor immunity through direct cytotoxicity and the induction of necrosis of tumor tissue." (PMID 33803078, 2021). "Tumour necrosis factor (TNF) is a pro-inflammatory cytokine, so named for its capability to induce tumour haemorrhagic necrosis." (PMID 34944729, 2021). "Taken together, it is suggested that TNF-α mediated the expression of adhesion molecules and their ligands after incubation of tumor cells with endothelial cells." (PMID 34222020, 2021). "KEGG analysis showed that the DEGs were mainly enriched in tumor-related pathways and TNF pathways in the CIS group." (PMID 33506037, 2021).
tumor (continued). "An increasing number of evidences shows that a small amount of TNF-α produced by tumor cells and stromal cells is an endogenous tumor promoter." (PMID 34079469, 2021). "Tumor-mediated TNF-α and VEGF production is also associated with integrin receptor alpha V and beta 3 and beta 5 (αvβ3/αvβ5) mediated neovascularization, which shows an active interaction between tumor cells and endothelial cells through TNF-α." (PMID 33986746, 2021). "Another pathway involves Fas ligand or TNF-related apoptosis-inducing ligand (TRAIL) “members of the tumor necrosis factor (TNF) family” interacting with tumor cells and inducing apoptosis." (PMID 34215336, 2021). "PER1 can promote cell apoptosis and expression of TNF-α, IL-6, and programmed death 1 (PD-1)/PD-L1, and inhibit tumor invasion and TUBB2B gene expression." (PMID 34220965, 2021). "Inflammatory cells often act as a critical source of various tumor-promoting inflammatory mediators, including ROS, cytokines such as TNF, IL-1, and IL-6, and growth factors that directly or indirectly support the entire process of tumor development." (PMID 34063828, 2021). "An early study revealed that TNF or IL‐1 promoted the adhesion of murine tumor cells to brain endothelium." (PMID 32761606, 2021). "NF-κB and TNF-α showed a very high positive correlation with tumour grade, high positive correlation with the presence of HER2 and metastasis, high negative correlation with the presence of ER and PR." (PMID 33776564, 2021). "In vitro CM from tumor-exposed human monocytes promoted TNF-α-induced CXCR4 expression on HUVECs via the Raf-Erk pathway." (PMID 34209679, 2021). "TNFα, as a weighted marker of Th1 cells, further mediates antitumor immunity and promotes tumor senescence." (PMID 34603277, 2021). "If stromal cells are the main source of TNFα within the tumor, CD4 T cells also produce TNFα in sufficient amount to inhibit CD8 T cells anti-tumor response but insufficient to impact tumor cells proliferation or viability." (PMID 33498483, 2021). "M1 macrophages eliminate pathogens and tumor cells by secreting agents such as tumor necrosis factor α (TNF-α), interleukin (IL)-12, RNS, and ROS, providing a pivotal contribution in the oxidative environment." (PMID 34680186, 2021). "In turn, TNF-α enhances the infiltration of immune cells to the tumor site by increasing the permeability of tumor blood vessels." (PMID 34203478, 2021). "NK cells are innate lymphoid cells involved in tumor immunosurveillance by inducing cancer cell lysis both directly (via perforin/granzyme system) or indirectly (via secretion of TNFα and IFNγ)." (PMID 34638439, 2021). "Future clinical implications of our study are the possibility of reducing the number of cancer drugs in a regimen from three to two and offering targeted therapy to specific tumor sites since they have higher TNF levels compared to normal tissue." (PMID 33542218, 2021). "Together, these results suggest that RRx-001 increased RBC adhesive potential to the endothelium under TNFα induced inflammation and hypoxia, as in the tumor microenvironment." (PMID 33946824, 2021). "TNFα, a proinflammatory cytokine highly expressed in tumor inflammatory environment, can transform BMSCs to TA-MSCs, which produce high-level CCR2 ligands to promote tumor growth by recruiting monocytes/macrophages." (PMID 33889575, 2021). "The mechanisms involved in the action of macrophages against tumor cells are the production of NO (nitric oxide) and TNF-α secretion, acting directly on tumor cells." (PMID 33946188, 2021). "TNF-α upregulates the expression of PD-L1 in tumor cells and T cell immunoglobulin and mucin domain 3 (TIM-3) in CD8+ TIL." (PMID 34367136, 2021). "In the inflammatory microenvironment of tumor, immune cells can release inflammatory factors such as TNF-α and IL-1β after immune cell infiltration, promote tumorigenesis, invasion and metastasis." (PMID 34120620, 2021).
tumor (continued). "Combination treatment with a neovasculature-targeted tumor necrosis factor (TNF) AcTakine mediates full tumor eradication and establishes immunological memory that protects against secondary tumor challenge." (PMID 34772757, 2021). "M1 macrophages are induced by interferon (IFN)γ and have anti-tumor activity, producing inflammatory cytokines such as interleukin (IL)-1β, tumor necrosis factor (TNF)-α, IL-6, and IL-23." (PMID 34685762, 2021). "A third study attributed the initial colonization in tumor tissues to tumor necrosis factor alpha (TNF-α) induced by the intravenous administration of Salmonella." (PMID 34203478, 2021). "For example, Zingg at al. observed that anti-CTLA-4 or IL-2 immunotherapy leads to TNFα amplification and T cell infiltration, resulting in EZH2 overexpression and loss of tumor control in melanoma mouse models." (PMID 34575678, 2021). "While L19-TNF preferentially accumulates at the tumor site and exhibits an improved therapeutic window compared to recombinant TNF, the biological activity and tolerability of the two products are comparable." (PMID 34576184, 2021). "The fusion of the TNF(I97A) mutant to the L19 antibody promoted restoration of anti-tumor activity upon accumulation on the cognate antigen, the alternatively spliced EDB domain of fibronectin." (PMID 34576184, 2021). "Both tumor and immune cells of solid tumors secrete tumor necrosis factor-α (TNF-α) which stimulates tumor cell growth survival, invasion, and metastasis, and inflammatory cell trafficking and neoangiogenesis." (PMID 34992504, 2021). "Tumor necrosis factor α (TNFα) is also one of the well‐studied tumor‐promoting cytokines, and its expression is enhanced in many cancers, which often indicates a poor prognosis." (PMID 34977871, 2021). "The T-cell potentiating virotherapy used here consisted of adenoviruses engineered to express tumor necrosis factor alpha and interleukin-2 in the tumor microenvironment." (PMID 34367166, 2021). "The effect of TNFα is pleiotropic, modulating the tumor microenvironment via paracrine mechanisms in the context of the cancer tissue." (PMID 33957885, 2021). "By linking the current result with previous experiments, it is suggested that the overexpressed adhesion molecules and their ligands on endothelial cells and tumor cells by microenvironment TNF-α were responsible for tumor metastasis." (PMID 34222020, 2021). "Amongst some of the well-studied growth factors, chemokines, and cytokines, TNF-α and IL-1β play a central role in inflammation that has been recognized as a key step in angiogenesis, tumor survival, and local invasiveness." (PMID 34571989, 2021). "Suppressed CAR T cell functions were observed in co-cultures with NECA alone, which included limited tumor killing and decreased TNF-α and IFN-γ production by the CAR T cells." (PMID 33776765, 2021). "Pro-inflammatory cytokines such as IL-1, IL-6, IL-8, IFN-γ, TNF-α, on one side are responsible for the growth and proliferation of immune and tumor cells, while on the other hand, increase tumor immune surveillance programs." (PMID 33924500, 2021). "Saline-treated tumor-bearing mice demonstrated a marked, though statistically insignificant, increase in serum IL-6 and TNF-α compared to tumor-free mice." (PMID 34445729, 2021). "M1 macrophages with tumoricidal effects can inhibit tumor growth and secrete pro-inflammatory cytokines like tumor necrosis factor-α (TNF-α), interleukin (IL)-6, and IL-12." (PMID 34062992, 2021). "Although we observed a decrease in tumor burden at early time points, the numbers and sizes of the tumors were found to be comparable in isotype- and anti-TNF–treated Zfp36ΔEP mice at later stages." (PMID 33497366, 2021). "TNF-α serves two functions – inducing hemorrhagic necrosis of the tumor by disrupting the vasculature and allowing the melphalan to locally accumulate in higher levels that would otherwise cause severe systemic toxicities." (PMID 33986746, 2021).
tumor (continued). "Anti-TNFα neutralizing Ab diminished cGAMP-induced anti-tumour growth by 47%, and reduced apoptosis of tumour ECs and whole tumour cells by 55% and 48%, respectively." (PMID 34285232, 2021). "In the TME, IFN-γ can subsequently lower the threshold for TNF activity, enabling full tumor eradication upon CD13 AFR delivery." (PMID 34772757, 2021). "Treatment of the LNCaP cell line employing iron oxide nanoparticles (IONPs) loaded with soluble TNF-α, and lactonic sophorolipids (LSLs) also had beneficial anti-tumor advantages." (PMID 34868907, 2021). "Enhanced tumor susceptibility to RIPK1-dependent death promotes T cell–derived, TNF-dependent tumor destruction." (PMID 34752416, 2021). "Total ROS levels in tumor tissue, tumor cell proliferation and hepatic levels of the proinflammatory cytokines IL-6 and TNF were reduced after chemically induced liver damage in Nox1-deficient animals." (PMID 33669824, 2021). "TNF-α is a well-known inflammatory factor and promoter of cancer, and, in this study, exhibited anti-tumor effects when assessed in an in vivo model of triple-negative breast cancer (TNBC)." (PMID 34960243, 2021). "TNF-α mitigates this barrier by disrupting tumor vasculature, reducing tumor IFP, and allowing chemotherapeutic agents to diffuse into the TME." (PMID 33986746, 2021). "It is well-known that IFNα, IFNγ and TNFα signaling mediate antitumor immunity whereas TGFβ signaling induces tumor immunosuppression 37-42." (PMID 33767579, 2021). "Tobacco smoke exposure following K-ras driven tumor initiation in mice had a tumor-promoting effect, via the induction of low-grade inflammation characterized by NF-κB-mediated production of IL-6 and TNF-α." (PMID 35221216, 2021). "Tumor cells can self-sustain this supportive environment by producing inflammatory cytokines like TNF-α, IL-1β, and IL-6." (PMID 34322780, 2021). "Th1 cells secrete pro-inflammatory cytokines such as Interferon gamma (IFN-γ), IL-2, TNF-α, IL-8, and IL-1β and can have anti-tumor effects." (PMID 34290984, 2021). "NOX5 activated intratumoral Src/nuclear factor‐κB signaling to stimulate secretion of tumor necrosis factor‐α (TNF‐α), interleukin‐1β (IL‐1β), and lactate from tumor cells." (PMID 34459125, 2021). "Although initially thought to be an effector for anti-tumor immunity, TNFα has been shown to have some pro-tumor functions." (PMID 35582030, 2021). "Expression levels of proinflammatory factors IL-6, IFN-γ, and TNF-α were also increased by CUMS compared with tumor group." (PMID 34650925, 2021). "TNFα can indirectly affect pain response by recruiting immune cells and regulate cytokine production within the tumor microenvironment." (PMID 33469141, 2021). "We observed increased expression of the effector cytokines TNF-α and IL-2 concomitantly with decreased secretion of IL-10 in culture supernatants of tumor-infiltrating leukocytes treated ex vivo with activin-A." (PMID 34548096, 2021). "The proinflammatory cytokine IL-6 is released by various immune cells triggered by IL-1β and TNF, but also produced by tumor cells directly as also proven for MPM with tumor-promoting effects." (PMID 33562138, 2021). "Real-time changes in NF-κB cell signaling dynamics within individual cells of a tumor were demonstrated using TNFα-induced activation during bioluminescence microscopy in vivo." (PMID 33652682, 2021). "Engineered tumor cells tolerated extensive TNFα overexpression well and easily overcame partial apoptosis induction." (PMID 33957885, 2021). "Previous studies have reported that tumor necrosis factor (TNF) interacts with tumor cells to trigger cytolysis or cell death." (PMID 33686952, 2021). "In further support, several recent Crispr-Cas screens in tumor cells have identified TNF death–signaling molecules to be critical in controlling tumor growth during immune checkpoint blockade." (PMID 34752416, 2021).